VIL1 (villin 1)
Description:
Epithelial cell-specific Ca(2+)-regulated actin-modifying protein that modulates the reorganization of microvillar actin filaments. Plays a role in the actin nucleation, actin filament bundle assembly, actin filament capping and severing. Binds phosphatidylinositol 4,5-bisphosphate (PIP2) and lysophosphatidic acid (LPA); binds LPA with higher affinity than PIP2. Binding to LPA increases its phosphorylation by SRC and inhibits all actin-modifying activities. Binding to PIP2 inhibits actin-capping and -severing activities but enhances actin-bundling activity. Regulates the intestinal epithelial cell morphology, cell invasion, cell migration and apoptosis. Protects against apoptosis induced by dextran sodium sulfate (DSS) in the gastrointestinal epithelium. Appears to regulate cell death by maintaining mitochondrial integrity. Enhances hepatocyte growth factor (HGF)-induced epithelial cell motility, chemotaxis and wound repair. Upon S.flexneri cell infection, its actin-severing activity enhances actin-based motility of the bacteria and plays a role during the dissemination.
Synonyms: VIL; D2S1471
Tractability: Antibody: its Gene Ontology location is reachable by antibodies, with high confidence; the Human Protein Atlas places it where antibodies can reach. PROTAC: ubiquitination databases record sites on it; its protein half-life has been measured.
Gene: Protein-coding gene on chromosome 2 (218,419,083 to 218,453,295, forward strand). Ensembl gene ENSG00000127831.
Subcellular location: Cytoplasm, cytoskeleton; Cell projection, lamellipodium; Cell projection, ruffle; Cell projection, microvillus; Cell projection, filopodium tip; Cell projection, filopodium
Subcellular location (Human Protein Atlas): Plasma membrane
Gene Ontology:
Molecular function: actin filament binding; calcium ion binding; identical protein binding; lysophosphatidic acid binding; phosphatidylinositol-4,5-bisphosphate binding; protein binding; protein homodimerization activity; cysteine-type endopeptidase inhibitor activity involved in apoptotic process; actin binding
Biological process: actin filament capping; actin filament depolymerization; actin filament polymerization; actin filament severing; barbed-end actin filament capping; cellular response to epidermal growth factor stimulus; cytoplasmic actin-based contraction involved in cell motility; epidermal growth factor receptor signaling pathway; epithelial cell differentiation; positive regulation of actin filament bundle assembly; positive regulation of actin filament depolymerization; positive regulation of cell migration; positive regulation of epithelial cell migration; positive regulation of lamellipodium morphogenesis; regulation of actin nucleation; regulation of cell shape; response to bacterium; actin polymerization or depolymerization; protein-containing complex assembly; regulation of lamellipodium morphogenesis; regulation of wound healing; actin filament organization; cellular response to hepatocyte growth factor stimulus; cytoskeleton organization; intestinal D-glucose absorption; and 6 more
Cellular component: actin filament bundle; extracellular exosome; filopodium; lamellipodium; microvillus; plasma membrane; ruffle; brush border; filopodium tip; cytoskeleton
Genetic constraint (gnomAD): Loss-of-function variants: 85 observed, 107.63 expected, observed/expected ratio (o/e) 0.79, 90% interval 0.66 to 0.95. The upper end of that interval is the gene's LOEUF score, 0.95, which puts it in group 4 of 6, group 1 being the genes least tolerant of losing a copy. Missense variants: 941 observed, 1,101.8 expected, observed/expected ratio (o/e) 0.85, 90% interval 0.81 to 0.9. Synonymous variants: 392 observed, 432.57 expected, observed/expected ratio (o/e) 0.91, 90% interval 0.83 to 0.99.
Homologues: Orthologues: chimpanzee VIL1 (99% identical), macaque VIL1 (98% identical), pig VIL1 (91% identical), mouse Vil1 (90% identical), rat Vil1 (89% identical), dog VIL1 (88% identical), guinea pig VIL1 (88% identical), rabbit VIL1 (86% identical), tropical clawed frog vil1 (68% identical), zebrafish vil1 (65% identical), Drosophila melanogaster Gel (31% identical), Caenorhabditis elegans gsnl-1 (21% identical). Paralogues in human: AVIL (61% identical), VILL (48% identical), GSN (44% identical), SCIN (41% identical), SVIL (29% identical), FLII (27% identical), CAPG (18% identical).